INS (insulin)
Diseases named in the same sentence as INS in open-access papers (continued):
Sharing a sentence is not in itself a finding about the gene and the disease.
Insulin resistance (continued). "While the mean insulin resistance was reduced by 10–15%, this was not statistically significant and was unlikely to be physiologically meaningful, given the fact that the overall increase in insulin resistance during pregnancy is two- to three-fold." (PMID 30360536, 2018). "Intranasal insulin administration was shown to inhibit forward projections from the ventral tegmental area to the nucleus accumbens and this was related to a reduction in food value but these modulatory effects of insulin were not present in participants with increased insulin resistance." (PMID 30445718, 2018). "However, the effects of sage on insulin sensitivity and glucose tolerance in a nutritional animal model of obesity and insulin resistance have not been described before." (PMID 29333341, 2018). "Thus, the glucose metabolic status was generally improved after SSA administration in the DM group due to the alleviated degree of insulin resistance without compromise of insulin secretion." (PMID 29853879, 2018). "Additionally, other work has suggested that EVs from obese subjects reduce insulin-stimulated glucose uptake and macrophage-derived EVs (M0 THP-1) interfere with GLUT-4 translocation in human adipocytes by decreasing p-Akt, thereby inducing insulin resistance." (PMID 30018986, 2018). "Furthermore, insulin resistance in the cavefish is not accompanied by increased levels of insulin meaning thereby that compensatory hyperinsulinemia does not inevitably follow insulin resistance." (PMID 30151194, 2018). "As shown presently and reported recently, insulin purified from guinea pig and other animal sources also depolarizes POMC neurons via a PI3K-induced activation of TRPC5 channels, and these neurons are a critical substrate in the development of sexually differentiated diet-induced insulin resistance." (PMID 29973869, 2018). "The etiology of insulin resistance in preterm infants is not well-understood; however, we have previously demonstrated in premature baboons that impaired insulin signaling in the skeletal muscle and liver, and impaired suppression of hepatic gluconeogenesis likely contribute." (PMID 30540820, 2018). "However, its direct effects on anti-diabetic activity such as insulin resistance and insulin secretion have not been examined." (PMID 30041479, 2018). "Therefore, ZFR presented significantly higher values of the insulin resistance (HOMA-IR) and pancreatic β cells functionality (HOMA-β) indexes and a decreased insulin sensitivity index (QUICKI), which indicate the development of insulin resistance and β-pancreatic cell dysfunction." (PMID 29614007, 2018). "After four weeks of red wine and dealcoholized red wine consumption, although fasting glucose did not change, the mean adjusted plasma insulin and Homeostatic model assessment Insulin Resistance (HOMA-IR) were decreased, indicating a beneficial role of polyphenols on insulin sensitivity." (PMID 30096779, 2018). "Last limitation could be that we have used a surrogate marker of insulin resistance (HOMA-IR) and not the golden standard to measure insulin resistance, i.e. insulin clamp technique." (PMID 30513089, 2018). "Insulin resistance is a hallmark of T2DM, in which insulin fails to trigger adequate glucose uptake, leading to accumulation of circulatory glucose as well as increased insulin levels." (PMID 30567565, 2018). "In the fetal heart, although insulin signaling may be altered due to insults (e.g., high-fat programming where the heart is exposed to excess FAs during development), overt insulin resistance does not present but may manifest later in life." (PMID 30344301, 2018). "Systemic insulin resistance induced in mice as a result of HFD reduces insulin receptor genes, insulin sensitive glucose transporter proteins, and activation of downstream effectors of insulin signaling pathways, such as phosphatidylinositol-3-kinase (PI3K) and Akt, in the hippocampus." (PMID 30619085, 2018).
Insulin resistance (continued). "The authors failed to indicate changes in insulin secretion, raising the question as to whether AS induces insulin resistance." (PMID 29534506, 2018). "Above all, PGRN may not be a good indicator of insulin resistance and insulin secretion function in mild obese children." (PMID 30151059, 2018). "In addition to less improvement in insulin resistance, patients with baseline BG120 below 8.1 mmol/l had a greater reduction in insulin secretion, which indicated that there was more chance of deteriorating glucose tolerance status after SSA treatment in these subjects." (PMID 29853879, 2018). "In insulin resistance, the body produces insulin but muscle, fat, and liver do not respond properly to insulin and thus cannot easily absorb glucose from the bloodstream, with progression from insulin resistance to prediabetes with impaired glucose tolerance and impaired fasting glucose over time." (PMID 30729102, 2018). "Indeed, the removal of TAG across adipose tissue was found to be impaired in obesity, insulin resistance and T2DM due to a reduced insulin-mediated stimulation of lipoprotein lipase (LPL) activity, suggesting less efficient removal of dietary lipids by adipose tissue in these subjects." (PMID 30234122, 2018). "Interestingly, fructose-induced hepatic insulin resistance was evident in young but not in adult rats, while whole body insulin sensitivity decreased both in fructose-fed young and adult rats." (PMID 29755364, 2018). "Consequently, the insulin sensitivity index, as represented by the Homeostasis Model Assessment of Insulin Resistance (HOMA-IR) was respectively reduced by 39, 60 and 78%, indicating a marked improvement in insulin sensitivity by both sage extract and rosiglitazone." (PMID 29333341, 2018). "In myocardial insulin resistance, the rate of fatty acid oxidation remains normal or may be increased, but the rate of glucose oxidation is usually decreased whether insulin-stimulated or noninsulin-stimulated." (PMID 29484207, 2018). "In the present cross-sectional study with subjects in secondary prevention for CVD, it can be seen that those who do not have insulin resistance have significantly lower anthropometric indices, as well as a lower plasma concentration of triacylglycerol, insulin and blood pressure." (PMID 29466985, 2018). "Second, as insulin was not measured throughout the survey period, insulin resistance, such as that evaluated by Homeostatic Model Assessment of Insulin Resistance (HOMAR-IR), could not be examined." (PMID 30310098, 2018). "Furthermore, we did not have biochemical data of blood levels of glucose and insulin and indicators of insulin resistance or β-cell function, such as Homeostatic Model Assessment for Insulin Resistance (HOMA-IR) and HOMA-β, for analyses." (PMID 30262775, 2018). "Meanwhile, DIDE could reverse the changes of these serum lipids, such as hyperglycemia and insulin resistance altered by the HFD feeding, which correlate with obesity-related metabolic disturbances that include hypertension, insulin resistance, impaired insulin secretion and cardiovascular disease." (PMID 30347741, 2018). "Lastly, a potential weakness of the study is that we had no data on insulin resistance (i.e., HOMA-IR index or fasting insulin), which is strongly associated with NAFLD and may contribute to the development of T2D." (PMID 29856820, 2018). "DeFronzo showed that peripheral insulin resistance is present in people with chronic renal failure, but hepatic insulin resistance may not be impaired." (PMID 29855339, 2018). "Further, MitoPQ induced insulin resistance in primary adipose and muscle tissue and recapitulated many of the features of insulin resistance, including impairment of insulin-regulated glucose transport independently of defects in insulin signaling without inhibiting AMPK-induced GLUT4 translocation." (PMID 29599292, 2018).
Insulin resistance (continued). "Hepatic IRS-1 and IRS-2 play a pivotal role in mediating insulin-dependent regulation of glucose and lipid metabolism; dysregulation of abundance and/or phosphorylation status of IRS-1 and IRS-2 in the liver are significant factors in the pathogenesis of insulin resistance and type 2 diabetes." (PMID 30225267, 2018). "Therefore, the increase in insulin in the absence of any change in glucose concentrations suggests that both maternal obesity and an offspring obesogenic diet independently led to insulin resistance." (PMID 29635288, 2018). "Our study further demonstrated that RES administration could reverse insulin resistance, decrease CCR2 expression in SAT and VAT, and reduce inflammation and macrophage infiltration of SAT and VAT, thus increasing insulin signaling molecules (such as IRS-1, GLUT4 and pAkt) in HFD-induced obese mice." (PMID 29967759, 2018). "In the developed heart with cardiac insulin resistance, the rate of glucose oxidation is usually decreased (independent of insulin-stimulation), whereas the rate of FA β-oxidation remains normal or may be increased." (PMID 30344301, 2018). "Fourth, insulin resistance could not be assessed in our study, because we did not measure insulin levels." (PMID 30224631, 2018). "At the individual level, the relationship between insulin concentrations and lipolysis will be difficult to predict because of the substantial variation in fasting insulin concentrations (or insulin resistance) between non-obese people with varying genetic backgrounds and lifestyles." (PMID 30541568, 2018). "Given that T2DM is characterized by insulin resistance, hyperinsulinemia and impaired insulin signalling, it is not surprising that an increased GSK-3β activity in T2DM might lead to an elevation of Aβ production and increased tau phosphorylation." (PMID 30355995, 2018). "When insufficient insulin production does not overcome insulin resistance, hyperglycemia can occur." (PMID 30400566, 2018). "Using the gold standard method, the glucose-insulin clamp, to assess metabolic insulin resistance, many studies in different populations found that insulin sensitivity was significantly lower among obese and nonobese PCOS women in comparison to healthy women within the same obesity subgroup." (PMID 29971102, 2018). "The exact role of mitochondrial control of inflammation in the aetiology of insulin resistance is not well established, but it provides another potential mechanism by which altered mitochondrial function could impact insulin action." (PMID 29538286, 2018). "Neither total T nor A4 was related to BMI, insulin, or insulin resistance." (PMID 30275830, 2018). "Although it is not clear how insulin resistance manifests in the central nervous system (CNS), many evidences suggest that different steps of the insulin signaling pathway might be altered." (PMID 29743868, 2018). "However, selective hypothalamic insulin resistance has been reported in humans, as obese men show responses in cognitive areas but not hypothalamic areas of the brain after intranasal insulin administration." (PMID 30043179, 2018). "In myocardial insulin resistance, the rate of FA β-oxidation remains normal or may be increased, but the rate of glucose oxidation is usually decreased whether insulin-stimulated or non-insulin-stimulated." (PMID 30344301, 2018). "BP reduction was similarly not correlated with insulin levels or insulin resistance." (PMID 29518898, 2018). "Although these differences could be technical and therefore should not be over interpreted, these miRNAs have also all been described to be regulated in model systems of muscle insulin resistance or T2DM or glucose uptake and insulin sensitivity, suggesting a functional relevance of this finding." (PMID 30050458, 2018).
Insulin resistance (continued). "Second, as POPs can directly reduce insulin secretion of beta cells, the role of POPs may be more prominent in the development of beta-cell dysfunction-dominant T2D rather than insulin resistance-dominant T2D." (PMID 30542326, 2018). "Insulin resistance occurs when cells no longer adequately respond to insulin." (PMID 30373146, 2018). "Thus even though fetuin-A does not bind to the same site as insulin on the extracellular portion of InsR, it attenuates insulin signaling, thereby contributing to insulin resistance." (PMID 30060600, 2018). "Finally, though the enrolled subjects in the two groups were of comparable fasting glucose, the PCOS patients had greater BMI and higher fasting insulin levels and HOMA-IR, which indicates obesity and insulin resistance is more prevalent in the enrolled PCOS women." (PMID 29344314, 2018). "Indeed, at present, strong evidences indicate that miRNAs are deeply involved in the post-transcriptional fine tuning of several insulin signaling components, from insulin receptor (INSR) to transcription factors; of note, some are altered in T2D and in insulin resistance." (PMID 30469501, 2018). "The results of this study show that insulin and HOMA levels rose with increasing liver fat, and that HOMA correlated with hepatic fat in a multivariable regression model thus indicating a strong relationship between insulin resistance and hepatic steatosis, as reported in other studies." (PMID 29351564, 2018). "Moreover, subjects with hyperuricemia showed higher glucose and insulin, either at fasting or as responses to OGTT, associated with higher insulin resistance and lower insulin sensitivity than those without hyperuricemia." (PMID 29505614, 2018). "As recent studies have indicated that agents capable of improving insulin sensitivity may be of great value in the treatment of T2DM, it is highly important to investigate whether insulin resistance and its clinical correlates can be reversed using therapies aimed at the neutralisation of TNF-α." (PMID 30914847, 2018). "Our data suggest that the impairment in insulin-mediated IRS–PI3K–Akt signaling promotes lipid accumulation and hepatic steatosis, which in turn contribute to chronic hepatic inflammation in the female liver under the conditions of hyperandrogenism and insulin resistance." (PMID 29719598, 2018). "Thus, the mice developed obesity and the expected symptoms of insulin resistance, and adding chicken hydrolysates to the diet did not prevent weight gain or elevated plasma glucose and insulin levels." (PMID 30597839, 2018). "Anyhow, results from a meta-analysis investigating the effect of fructose uptake on insulin sensitivity concluded that fructose consumption induces hepatic insulin resistance in normal weight, nondiabetic subjects, but short- and medium-term fructose uptake does not promote insulin resistance." (PMID 30200659, 2018). "Likewise, it is the loss of insulin sensitivity that explains why obese individuals are more likely to develop T2D and CVD, but not all overweight/obese individuals present insulin resistance." (PMID 29951035, 2018). "In terms of the metabolic markers available in CAPS, insulin was only measured in a small proportion of subjects and was not measured in Phase 3, thus insulin resistance could not be estimated." (PMID 29098427, 2018). "In summary, among nonobese women with PCOS, some display insulin resistance that may be due to abdominal obesity and others are not more insulin resistant than the general population." (PMID 29971102, 2018). "Additionally, women with PCOS and insulin resistance typical of individuals with T2DM have more profound hyperandrogenemia, higher visceral fat, and a lower non-oxidative glucose metabolism compared to women with PCOS who are insulin sensitive." (PMID 30377436, 2018).
Insulin resistance (continued). "Regarding the association between the changes in the T cell subset and insulin resistance, a significant positive correlation was observed between the AUC0–120 min of CD8+ and the change in the FFA level, but not the glucose or insulin levels, after glucose loading." (PMID 29615971, 2018). "T2DM occurred either when the pancreas could not produce enough insulin (insulin hyposecretion), or when the body cannot effectively use the insulin it produces (insulin resistance)." (PMID 30326632, 2018). "As expected, obesity showed positive associations with homeostatic model assessment for insulin resistance (HOMA-IR), triacylglycerol, insulin, plasma levels of non-esterified fatty acids, and cholesterol ester transfer protein activity and negative associations with plasma antioxidant levels." (PMID 30365817, 2018). "Therefore, in our opinion, currently it is not possible to select either a universal ‘cut-off’ point in order to define insulin resistance, nor to define ‘the best’ method of assessment of insulin resistance, for the purpose of clinical practice." (PMID 29436386, 2018). "While hyperglycemia, elevated serum triglycerides and insulin resistance were observed in the HFD group, supplementation with TT for 14 weeks significantly improved overall glucose homeostasis by decreasing fasting blood glucose level and improving glucose and insulin tolerances." (PMID 30054493, 2018). "The pathogenesis of T2DM involves two basic pathological defects: impaired insulin secretion and insulin resistance (IR), which may be defined as reduction or lack of insulin sensitivity to the target tissues, such as adipose tissue, muscles, and the liver." (PMID 30271528, 2018). "As the disease progresses, even insulin injection may not help with blood glucose control, due to severe insulin resistance in the late stage." (PMID 30602666, 2018). "In addition, saturated fatty acid induces insulin resistance due to its antagonistic action on the PPAR-γ coactivator (PGC1-alpha), which promotes the expression of mitochondrial genes involved in oxidative phosphorylation and insulin-mediated glucose uptake." (PMID 29466985, 2018). "The most relevant changes responsible for insulin resistance might involve the expression and/or activity of insulin receptor β-subunit, Akt, GLUT4, AMPK and many other intracellular signals known to be involved in the insulin effect." (PMID 30483144, 2018). "Apart from a single state of hyperglycemia, type 2 diabetes is usually accompanied by obesity-induced insulin resistance and hyperinsulinaemia, which could have a nonnegligible effect on insulin signaling and lead to cardiac hypertrophy." (PMID 28883902, 2017). "GLUT4-vesicule fusion to plasma membrane is also dependent on Ca2+ signaling, and therefore, disturbances in Ca2+ homeostasis could be a factor involved in insulin resistance, independent of impaired insulin signaling." (PMID 28676863, 2017). "Although a dose related response was found for rosiglitazone in OGT, FBS and fasting plasma insulin, it could not significantly reduce BMI, FBS, IGT, plasma insulin and insulin resistance as well as insulin levels after glucose ingestion at different doses." (PMID 29282412, 2017). "Therefore, we consider the results that CML correlates with ACU-IRI and ISI, but not GDR and HOMA-IR, which means CML mainly affects insulin secretion ability rather than insulin resistance." (PMID 28695132, 2017). "Insulin resistance has been suggested as a key factor driving neural deficits in obesity, and it was therefore predicted that HOMA-IR score, which offers an estimate of insulin sensitivity, would reflect memory impairments and neural activity, potentially to a greater degree than BMI." (PMID 28093279, 2017).